RAC1 (Rac family small GTPase 1)
Diseases named in the same sentence as RAC1 in open-access papers (continued):
Sharing a sentence is not in itself a finding about the gene and the disease.
skin cancer (11 papers, 2011 to 2023). "In human CRC, although the RAC1 mutation rate was relatively low compared to other cancer types like skin cancer, the overexpression of RAC1 protein was noticed and it tightly linked to tumor stage and metastasis." (PMID 33406731, 2021). "An alternative explanation for the occurrence of SCCs in K14 HPV-8/Rac1-EKO mice would therefore be that the loss of Rac1 disrupts the integrity of the epidermal stem cell niche, which normally protects from UV-light induced skin tumor formation." (PMID 27506937, 2016). "The RAC1 GEF TIAM1 is a candidate therapeutic target as TIAM1 is a RAS effector required for oncogenic RAS-induced skin cancer." (PMID 37748077, 2023). "A study investigating the role of Rac1 activity in the malignant progression of sebaceous skin tumours identified DHCR24 as a target gene." (PMID 35626014, 2022). "For example, although RAC1 is generally thought to play a tumor‐promoting role in tumor development, some research indicates that RAC1 suppresses tumor progression in renal carcinomas and skin cancers." (PMID 31314174, 2019). "Targeted deletion of Rac1 or inhibition of Rac1 activity by the chemical inhibitor NSC23766 in epidermal keratinocytes reduced skin tumor formation in a chemical skin carcinogenesis model." (PMID 27506937, 2016). "Our results suggested that hyperactive Rac1 recruited and interacted with CD11b+Gr1+ cells, inducing keratin 17-regulated inflammation and promoting skin tumor formation." (PMID 24962779, 2014). "In a DMBA/TPA-induced mouse skin tumor model, inhibition of Rac1 activity and depletion of CD11b+Gr1+ cells resulted in significant tumor formation." (PMID 24962779, 2014). "Based on our findings that Rac1 was hyperactivated in SCC tissue, we used a mouse skin tumor model induced by DMBA/TPA to test the function of Rac1 in SCC carcinogenesis." (PMID 24962779, 2014). "We previously showed that Rac1 is crucial for Ras-dependent skin tumor formation and regulates crosstalk between keratinocytes and immune cells." (PMID 24962779, 2014). "We previously found that Rac1 is responsible for DMBA/TPA-induced skin tumor formation using keratinocytes restricted Rac1 knockout mice." (PMID 24962779, 2014). "In conclusion, Rac1 appeared to promote skin tumor formation by activation of an IFN-keratin 17 loop and through recruitment of CD11b+Gr1+ cells." (PMID 24962779, 2014). "Rac1 expression in skin tumor tissue was similar to that of in normal skin, but Rac1 activation in tumors was significantly higher than in normal skin." (PMID 24962779, 2014). "NDV infection preferentially replicate in Rac1-overexpressing cells, and inhibition of Rac1 protein also blocked the growth of the skin carcinoma mutant cell line." (PMID 23586025, 2013). "Since, for human skin, the most relevant environmental carcinogen is UV-light, we asked whether Rac1 activity plays a similar role in UV-light induced skin tumor formation." (PMID 27506937, 2016). "Skin tumors in K14 HPV-8/Rac1-EKO mice were more flat than those in K14 HPV-8 mice." (PMID 27506937, 2016). "In this study, we have investigated the mechanism by which Rac1 promotes skin tumor formation." (PMID 24962779, 2014). "Given our results suggesting that Rac1 functioned in keratinocyte proliferation and differentiation, we asked whether Rac1 regulated an inflammatory microenvironment that promoted skin tumor formation." (PMID 24962779, 2014). "Here we discuss the regulation of Rac1 on skin tumor formation and its relationship." (PMID 24962779, 2014). "Given the proposed role of Rac1 in skin tumor formation and the known importance of UV-light as the major carcinogen in skin, we asked whether UV-light-induced skin carcinogenesis is influenced by Rac1." (PMID 28277539, 2017). "Thus, Rac1 might be a key molecular link between inflammation and skin tumor formation." (PMID 24962779, 2014). "We found that Rac1 activation but not expression is involved in skin tumor formation." (PMID 24962779, 2014).
acute myeloid leukemia (10 papers, 2016 to 2025). Acute myeloid leukemia (AML) is a group of neoplasms arising from precursor cells committed to the myeloid cell-line differentiation. "Ras-related C3 botulinum toxin substrate 1 (Rac1) is a GTPase implicated in cell migration and homing of hematopoietic cells to the hematopoietic niche, and is commonly overexpressed in acute myeloid leukemia (AML)." (PMID 38185059, 2024). "Rac1 is also overexpressed in acute myeloid leukemia cells, where it enhances migration and cell growth, and is linked to chemoresistance." (PMID 27104658, 2016). "Rac1 GTPase has long been recognized as a critical regulatory protein in different cellular and molecular processes involved in cancer progression, including acute myeloid leukemia." (PMID 29228706, 2017). "In acute myeloid leukemia (AML), UCA1 can be used as an endogenous sponge to compete with miR-126, which in turn suppresses activation of the PI3K/AKT signaling pathway by inhibiting the expression of RAS-related C3 botulinus toxin substrate 1 (RAC1)." (PMID 33777227, 2021).
medulloblastoma (10 papers, 2013 to 2026). A malignant, invasive embryonal neoplasm arising from the cerebellum. "While it remains to be determined, it is possible that in medulloblastoma cells as well, loss of Na,K-ATPase function could modulate RhoA or Rac1 activity to inhibit EGF-induced motility and stress fiber formation." (PMID 25052069, 2014). "We describe here distinct modulation of the actin cytoskeleton and inhibition of migration in these two medulloblastoma cell lines through targeting critical signalling pathways upstream of Rac1." (PMID 36377725, 2022). "In the present report, we demonstrate that both MKI and the PI3K inhibitor reduce levels of activated Rac1 in two medulloblastoma cell lines representing two molecularly defined medulloblastoma entities with high metastatic potential." (PMID 36377725, 2022). "Here, we show that PI3K inhibition as well as inhibition of tyrosine kinase driven signalling pathways in medulloblastoma cells decrease activated Rac1 particularly in MEB‐Med‐8A." (PMID 36377725, 2022). "Our results show that these clinically available therapeutics can suppress Rac1 activation and decrease migratory capacity in medulloblastoma." (PMID 36377725, 2022). "Here, we document in two molecular types of medulloblastoma with high metastatic potential, activation of cytosolic Rac1, and pronounced phosphorylation of AKT and Erk1/2." (PMID 36377725, 2022). "Here, we demonstrate that Rac1 is present in the nuclear and cytoplasmatic compartments in both medulloblastoma cell lines." (PMID 36377725, 2022). "Targeting the small Rho GTPases Rac1 has been shown to effectively impair medulloblastoma cell migration in vitro." (PMID 36377725, 2022). "Here, we show that Rac1 is expressed in both the cytoplasm and nucleus in the medulloblastoma cell lines Daoy and MEB‐Med‐8A representative of two high risk medulloblastoma entities." (PMID 36377725, 2022). "In this study, we illustrated the multifaceted role of Pictilisib, Pazopanib and Sorafenib as inhibitors of Rac1, as modulators of the cytoskeleton and migration in medulloblastoma." (PMID 36377725, 2022). "Rac1 expression has been confirmed by immunohistochemistry in a series of medulloblastoma specimens and has been shown to act as a central effector of migration in medulloblastoma models." (PMID 36377725, 2022). "Transgenic mouse strains and human medulloblastoma (MB) tissue samples were utilized to examine the role of Rac1 in Hh-directed limb bud development and MB progression." (PMID 35154488, 2022). "The small Rho GTPase Rac1 has long been identified as a critical factor in migration, invasiveness, and metastasis in an array of cancers including medulloblastoma." (PMID 36377725, 2022). "The CaMKK pathway has been shown to promote cerebellar granule precursor migration and differentiation during normal cerebellar development via CaMKIV, while CaMKK/CaMKI cascade regulates basal medulloblastoma cell migration via Rac1." (PMID 34263253, 2021). "In many cancers, such as medulloblastoma, breast, ovarian, and various other cancers, p130Cas activates Rac1 and affects cancer progression 23-25." (PMID 33042270, 2020). "The migratory capacity of medulloblastoma cells is regulated by the CaMKK/CaMK-I pathway and the small G protein Rac1, as well as its GDP/GTP-exchange factor GEF/Rac1." (PMID 31991573, 2020). "Indeed, it was shown that Gli1/2 nuclear translocation in response to Shh requires Rac1 activation, and Rac1 is involved in the progression of Shh-type medulloblastoma." (PMID 36681682, 2023). "Thus, our in vitro observations provide new insights into different strategies of blocking Rac1 and inhibiting migration in medulloblastoma employing clinically available agents paving the way for confirmatory studies in in vivo models." (PMID 36377725, 2022). "Thus, Rac1 activation has been shown by genetic interference to drive medulloblastoma migration in vitro." (PMID 36377725, 2022).
medulloblastoma (continued). "In addition, pharmacological CaMKK inhibition blocks both estrogen-induced Rac1 activation and medulloblastoma migration." (PMID 34263253, 2021). "DDX3 depletion suppressed the protein expression of RAC1 in medulloblastoma." (PMID 34307388, 2021). "Interestingly, recent studies showed that Rac1 is overexpressed in medulloblastoma tumors and that Rac1 depletion strongly inhibits medulloblastoma cell invasion." (PMID 25052069, 2014). "Also, Erk phosphorylation may be modulated by the counter‐balancing effects of Rac1 and RhoA activity levels in medulloblastoma." (PMID 36377725, 2022). "Upstream of Rac1, the PI3K/AKT pathway as well as PDGFR signalling, triggering the (RAF) RAS/MAPK/ERK cascade govern migration and proliferation in medulloblastoma." (PMID 36377725, 2022).
oral cancer (10 papers, 2014 to 2022). "OSF significantly induced the EMT in oral cancer cells and downregulated epithelial markers, such as E‐cadherin, but significantly elevated vimentin, fibronectin, N‐cadherin, RhoA, Rac‐1 and FAK." (PMID 34528373, 2021). "Previous studies have demonstrated that RAC1 is involved in the cell migration and survival in oral cancers." (PMID 34176441, 2021). "DEPDC1B affects the loading and augmentation of ERK1/2 activity by Rac1 GTP, which subsequently causes colony formation in oral cancer cells." (PMID 25091805, 2014). "By using genetic approaches, we provided evidence that DEPDC1B regulates anchorage-independent growth mediated through Rac1 in oral cancer cells." (PMID 25091805, 2014). "We confirmed that the cell proliferation ability induced by DEPDC1B was abolished with the coexpressed Rac1 N17 proteins in oral cancer cells." (PMID 25091805, 2014). "Our data revealed that DEPDC1B affected Rac1 GTP loading and augmented ERK1/2 activity, causing subsequent colony formation in oral cancer cells." (PMID 25091805, 2014). "To confirm the expression of DEPDC1B in such oral cells, we employed a PAK PBD pull-down assay to test whether the DEPDC1B expressed in oral cancer cells induced GTP loading in Rac1 proteins." (PMID 25091805, 2014). "Ahuja P and Singh K showed that DEPDC1B promoted oral cancer cell growth, invasion, and anchorage independent growth mediated by the interaction between DEPDC1B and Rac1." (PMID 34032605, 2021). "DEPDC1B, acted as a potentially oncogenic protein in oral cancer patients, contributing to the sustained elevation of ERK1/2 activity throughout the stimulation of the GDP-GTP exchange in Rac1." (PMID 25091805, 2014). "The anchorage-independent growth ability in soft agar of the mutant Rac1 (Rac1 N17) coexpressed with DEPDC1B in these cells and oral cancer cells was examined and compared with DEPDC1B cells." (PMID 25091805, 2014). "The precise function of DEPDC1B is uncharacterized; however, in recent studies it has been shown to promote cell growth, invasion, and anchorage-independent growth of oral cancer cells, the function being mediated by the direct physical interaction of DEPDC1B with Rac1 protein." (PMID 27034663, 2016). "Because the small GTPase Rac1 acted as a bridge for DEPDC1B to induce cellular functions, we tested the role of DEPDC1B to see whether it potentiated tumor formation in an oral cancer cell line, KB." (PMID 25091805, 2014). "Our model suggested that DEPDC1B was a positive modulator of Rac1 in oral cancer cell lines cultured in both adherent and nonadherent conditions." (PMID 25091805, 2014). "Our results suggested a novel route by which DEPDC1B regulates Rac1 activation and modulates ERK1/2 activities, and offer an explanation for the mechanism by which DEPDC1b contributes to anchorage-independent growth in oral cancer cells." (PMID 25091805, 2014). "In oral carcinoma, however, due to disruption of HPV E2, which is a viral tumor suppressor and is known to downregulate the expression of DEPDC1B, highly expressed DEPDC1B could interact with RAC1 and result in cell invasion/metastasis." (PMID 35095994, 2021).
pancreatic ductal adenocarcinoma (10 papers, 2011 to 2025). An infiltrating adenocarcinoma that arises from the epithelial cells of the pancreas. "Wild-type Vav1 and mutant K-Ras synergistically accelerate pancreatic acinar-to-ductal metaplasia (ADM), thus leading to pancreatic ductal adenocarcinoma (PDAC), depending on Vav1’s activity as a GEF for Rac1." (PMID 32277014, 2020). "Transforming growth factor (TGF)-β1 promotes progression of pancreatic ductal adenocarcinoma (PDAC) by enhancing epithelial-mesenchymal transition, cell migration/invasion, and metastasis, in part by cooperating with the small GTPase Rac1." (PMID 24378395, 2014). "Transforming growth factor β (TGFβ) promotes pancreatic ductal adenocarcinoma (PDAC) primarily through its non-canonical (non-Smad) signaling arms, including signaling by the small GTPase RAC1." (PMID 33266416, 2020).
sarcoma (10 papers, 2010 to 2025). A usually aggressive malignant neoplasm of the soft tissue or bone. "The oncogenic, activating Rac1 N92I mutation was discovered in the human sarcoma cell line HT1080 and the C157Y mutation was discovered in patients with cranial malformations and has, as yet, unclear effects on Rac1 activity." (PMID 34252134, 2021). "The mutant form of Rac1 (N92I) found in human sarcoma cell line HT1080 not only makes Rac1 highly carcinogenic, but also resists endoplasmic reticulum stress." (PMID 34079763, 2021). "To determine whether galectin-3 induced the activation of Rac1-dependent signaling pathways in sarcoma cells, we evaluated whether phosphorylated PAK accumulated in focal contacts upon exposure to galectin-3." (PMID 22216245, 2011). "However, in all three rodent fibroblast cell lines previously evaluated, it has been shown that expression of activated Rac1 or Cdc42 potentiated the ability for these cells to form sarcomas following their subcutaneous injection into athymic mice." (PMID 20067638, 2010).
Anxiety (9 papers, 2015 to 2024). Intense feelings of nervousness, tension, or panic often arise in response to interpersonal stresses. "Studies suggested the influences of acetylation and sumoylation in anxiety-like behaviors, for example, increased acetylation of Arc SARE attenuated anxiety-like behavior in adult rats, besides, sumoylation of Rac1 and serotonin 1a receptor regulated anxiety-like behavior." (PMID 36344488, 2022). "Post-hoc analysis showed that the average number of arm entries and latency to the first arm entry were not significantly different between the control group and the W56 group, suggesting that ambulatory activity and anxiety levels were not affected by presynaptic Rac1 inhibition." (PMID 38562715, 2024).
esophageal squamous cell carcinoma (9 papers, 2010 to 2024). Esophageal squamous cell carcinoma (ESCC) is a type of esophageal carcinoma (EC) that can affect any part of the esophagus, but is usually located in the upper or middle third. "Nuclear factor 45 promotes cell invasion in esophageal SCC (ESCC) cell lines by upregulating Rac1/Tiam1 signaling through the 14–3-3ε protein." (PMID 38279176, 2024). "It was reported that suppressing glycolytic enzymes by inhibiting RAC1 showed reduced cisplatin resistance in esophageal squamous cell carcinoma." (PMID 32878621, 2020). "Rac1 is highly expressed in esophageal squamous cell carcinoma (ESCC) and is closely related to poorer prognosis in ESCC patients as well as enhanced RAC1 expression and increased cell proliferation, migration, and chemoresistance." (PMID 35682879, 2022). "Recently, we found that Rac1 played an important role of tumor-promoting in the progression of esophageal squamous cell carcinoma (ESCC) and the expression of Rac1 was positively related to cisplatin resistance in ESCC cells." (PMID 33604328, 2020).
gastric adenocarcinoma (9 papers, 2018 to 2022). "Rac1 is implicated in treatment resistance in multiple cancers and Rac1 inhibition increases sensitivity to doxorubicin for squamous cell carcinoma cells, 5-fluorouracil and cisplatin in gastric adenocarcinoma spheroids, and fludarabine for chronic lymphocytic leukemia." (PMID 30261690, 2018). "It is evidenced that inhibition of Rac1 activity can be used to overcome treatment resistance, which has also been confirmed in cisplatin-resistant gastric adenocarcinoma cells and trastuzumab-resistant BC cells." (PMID 34079763, 2021). "In a recent study, high Rac1 activity in gastric adenocarcinoma tissues is correlated with worse overall survival." (PMID 32392742, 2020). "Rac1 promotes the EMT program in gastric adenocarcinomas and the acquisition of a cancer stem cell state." (PMID 30159893, 2019). "Interestingly, Rac1 was recently shown to be important in maintaining stem cells of the normal epidermis and cancer stem cells in gastric adenocarcinoma." (PMID 36077697, 2022). "Rac1 inhibition in gastric adenocarcinoma cells blocks EMT and CSC phenotypes and thus prevents metastasis and may augment chemotherapy." (PMID 30159893, 2019). "The inhibition of Rac1 by shRNA, or NSC23766, reverses chemotherapy resistance in gastric adenocarcinoma cell lines." (PMID 32392742, 2020).